SOCS1 (suppressor of cytokine signaling 1)
Diseases named in the same sentence as SOCS1 in open-access papers (continued):
Sharing a sentence is not in itself a finding about the gene and the disease.
skin infection (2 papers, 2021 to 2025). An inflammatory process affecting the skin, caused by bacteria, viruses, parasites, or fungi. "Together this data suggests that SOCS-1 may be a potential target for future therapeutic intervention in skin infections and may benefit not only to highly susceptible patient populations but also to more broad patient populations with other bacterial infections of the skin." (PMID 33690673, 2021). "Together, these data suggest that phagocyte SOCS-1 expression negatively impacts MRSA skin infection outcomes." (PMID 33690673, 2021). "To explore the role of SOCS-1 in S. aureus skin infection, we initially examined Socs1 mRNA expression in the MRSA-infected skin of C57BL6/J mice." (PMID 33690673, 2021). "Myeloid-specific SOCS-1 expression is detrimental to skin infection by inhibiting type I interferon (IFN)-dependent nitric oxide production and bacterial killing." (PMID 33690673, 2021). "As neutrophils and macrophages are required to control MRSA skin infection, we further studied the role of myeloid-specific SOCS-1 actions during skin infection." (PMID 33690673, 2021). "Whether SOCS-1 regulates the production of type I and type II IFNs during skin infection remains to be determined." (PMID 33690673, 2021). "Here, we identified a heretofore unknown role of the intracellular negative regulator of the immune response suppressor of cytokine signaling 1 (SOCS-1) in the control of S. aureus skin infection." (PMID 33690673, 2021). "Next, we examined the impact of SOCS-1 inhibition on the inflammatory milieu during skin infection." (PMID 33690673, 2021). "We hypothesize that SOCS-1 negatively impacts S. aureus skin infection outcomes by limiting phagocyte host defense and the inflammatory response." (PMID 33690673, 2021). "Overall, these data demonstrate a role for SOCS-1-mediated type I interferon actions in host defense and inflammation during MRSA skin infection." (PMID 33690673, 2021). "Next, we aimed to link SOCS-1/type I IFN and NO in in vivo MRSA skin infection." (PMID 33690673, 2021). "We hypothesized that SOCS-1 decreases type I interferon production and IFNAR-mediated antimicrobial effector functions, limiting the inflammatory response during skin infection." (PMID 33690673, 2021). "However, while iKIR plus IgG control decreased bacterial load, the treatment of mice with anti-IFNGR antibody did not prevent iKIR effects on bacterial clearance, demonstrating that IFNγ is not solely involved in the inhibitory effects of SOCS-1 during MRSA skin infection." (PMID 33690673, 2021).
ulcers (2 papers, 2023 to 2025). "In this study, SOCS-1, -3, -5, and -com, which are known to play a positive role in wound healing, were gene-delivered to ADMSCs using a non-viral method to confirm the improvement effect in ulcers." (PMID 37508509, 2023).
acute GVHD (1 paper, 2022). "Moreover, high expression of SOCS1 in T cells from patients correlates with low acute GVHD occurrence after HSCT." (PMID 35585676, 2022).
Acute hepatitis (1 paper, 2017). Acute hepatic injury resulting from inflammation typically accompanied by increased serum alanine transaminase activity. "In the current study, Sophocarpine pretreatment significantly inhibited STAT1 activity and increased the expression of SOCS1, subsequently downregulating its signaling proteins T-bet and inhibiting the production of Th1 cytokines, which protects mice from ConA-induced acute hepatitis." (PMID 28377718, 2017).
Adult onset (1 paper, 2016). Onset of disease manifestations in adulthood, defined here as at the age of 16 years or later. "Therefore, to explore the combined loss of SOCS1 and SOCS3 in inflammation, we determined the effects of post-natal inactivation of SOCS3 on disease development and severity in the Ifng-/-;Socs1-/- model of adult-onset inflammatory disease." (PMID 27583437, 2016).
airway hyperresponsiveness (1 paper, 2015). "Having established that SOCS1 levels are increased in patients with AA and related to airway hyperresponsiveness to histamine, the ability of SOCS1 to modulate rhinovirus induction of interferons in BECs in vitro was examined." (PMID 25630941, 2015). "Indeed, we found that bronchial epithelial SOCS1 expression correlated with the number of positive skin prick test responses and airway hyperresponsiveness but not exacerbation numbers, suggesting that SOCS1 can be increased in response to but not limited to allergic inflammation." (PMID 25630941, 2015).
alcoholic liver damage (1 paper, 2025). "According to earlier in vivo and in vitro findings, SOCS1 is essential in how BA influences M2 macrophage repolarization to mitigate alcoholic liver damage." (PMID 40361210, 2025).
alopecia areata (1 paper, 2022). Loss of scalp and body hair involving microscopically inflammatory patchy areas. "Other genes are related to the progression of alopecia areata after the IP collapse of hair follicles such as the suppressor of cytokine signaling-1 (SOCS1) gene, FAS and FAS ligand genes, the neurogenic locus homolog 4 (NOTCH4) and some chemokines encoding genes." (PMID 36292745, 2022).
arteriosclerosis (1 paper, 2017). A vascular disorder characterized by thickening and hardening of the walls of the arteries. "A previous study suggests that SOCS1 prevents graft arteriosclerosis by preserving endothelial cell function, with a reduction of inflammatory cytokines produced by infiltrating immunocytes." (PMID 28915645, 2017).
atopic asthma (1 paper, 2015). An asthma that is characterized by symptoms that are triggered by an allergic reaction caused by inhaled allergens such as dust mite allergen, pet dander, pollen and mold. "We next investigated the abundance of SOCS1 and SOCS3 proteins in biopsy specimens of adults with uninfected mild-to-moderate atopic asthma (AA) compared with nonatopic nonasthmatic (NANA) adult control donors." (PMID 25630941, 2015).
autoimmune gastritis (1 paper, 2025). Inflammation of the body fundic mucosa of the stomach. "Interestingly, we describe for the first time the presence of autoimmune gastritis in SOCS1 haploinsufficiency." (PMID 41249727, 2025).
autoimmune thyroiditis (1 paper, 2025). "Total glucosides of paeony (TGP) can regulate the expression of SOCS1 in rats with autoimmune thyroiditis, enhance the expression of JAK1, JAK2, STAT3, and STAT5, thereby affecting the JAK/STAT signaling pathway." (PMID 40584613, 2025).
basophilic leukemia (1 paper, 2018). "TargetScan analysis predicted that the binding of miR-122a-5p to the 3′ UTR of SOCS1 and miR-122a-5p would decrease luciferase activity associated with 3′ UTR of SOCS1 in rat basophilic leukemia (RBL2H3) cells." (PMID 30459600, 2018).
Behçet’s disease (1 paper, 2025). "Based on these research findings, it is proposed that DNA methylation alterations within the SOCS1 gene could play a role in modulating its expression thereby facilitating the development of Behcet’s disease." (PMID 40755762, 2025).
biliary atresia (1 paper, 2022). A rare, biliary tract disease characterized by progressive obliterative cholangiopathy of the intra- and extrahepatic bile ducts, occurring in the embryonic/ perinatal period, leading to severe and persistent neonatal jaundice and acholic stool. "In patients with biliary atresia or PBC, an inverse correlation between miR-155 and the suppressor of cytokine signalling 1 (SOCS1) has been reported." (PMID 36139455, 2022).
bipolar disorder (1 paper, 2021). A disorder of the brain that causes unusual shifts in mood, energy, activity levels and the ability to carry out day-to-day tasks. "SOCS1 mRNA levels were also significantly higher in patients with bipolar disorder, but this finding remained positive in male patients only if different genders were analyzed separately." (PMID 34393859, 2021). "SOCS1 had also been investigated in other mood disorder, namely bipolar disorder." (PMID 34393859, 2021).
brucellosis (1 paper, 2024). Brucellosis is a bacterial infection that spreads from animals to people via unpasteurized dairy products or by exposure to contaminated animal products or infected animals. "Consistently, these genes associated with ‘interferon‐gamma response’ (e.g., IFNG, IRF1, SOCS1) are also enriched in brucellosis patients." (PMID 39135683, 2024).
C. perfringens infection (1 paper, 2023). "As for day 19, C. perfringens infection significantly increased STAT3 expression, but the SOCS1 expression was also raised." (PMID 38136901, 2023).
carotid atherosclerosis (1 paper, 2017). A thickening and loss of elasticity of the walls of carotid arteries that occur with formation of atherosclerotic plaques. "There is a correlation between the SOCS1 gene polymorphism and carotid atherosclerosis." (PMID 28915645, 2017).
cervical squamous cell carcinoma (1 paper, 2023). A squamous cell carcinoma arising from the cervical epithelium. "* Increased in serum exosomes from patients with cervical squamous cell carcinoma.* miR-142-5p targets SOCS1, which can modulate cytokine signaling and can induce a remodeling of lymphatic vessel." (PMID 36936170, 2023).
cervical tumor (1 paper, 2020). "However, the role of SOCS1 remains controversial because the overexpression of SOCS1 in cervical tumor cells confers radioresistance." (PMID 33076315, 2020).
Chlamydia infection (1 paper, 2021). "IL-10 nanoparticle capsules as therapeutic strategies can modulate the release of IL-6, IL-12p40, suppressor of cytokine signaling 1 (SOCS1), and SOCS3 by mitigating the inflammatory response against Chlamydia infection in macrophages." (PMID 34093535, 2021).
cholangiocarcinoma (1 paper, 2020). A carcinoma that arises from the intrahepatic biliary tree (intrahepatic cholangiocarcinoma) or from the junction, or adjacent to the junction, of the right and left hepatic ducts (hilar cholangiocarcinoma). "It is noteworthy that BRAF, which also negatively correlates with SOCS1, has been previously reported to be commonly found in cholangiocarcinoma but not in HCC." (PMID 32807134, 2020).
chondrosarcoma (1 paper, 2013). A malignant cartilaginous matrix-producing mesenchymal neoplasm arising from the bone and soft tissue. "Because MMPs production is induced by IL-1β, we evaluated the inhibitory effects of SOCS1 on MMPs synthesis by altering SOCS1 expression levels in the SW1353 chondrosarcoma cells." (PMID 24238405, 2013).
chordoma (1 paper, 2020). Chordomas are rare malignant tumors arising from embryonic remnants of the notochord in axial skeleton. "For instance, Duan and colleagues found that low miR-1 expression in chordoma tissues promoted the proliferation and invasion of tumor cells by upregulation of slug, while miR-155 led to aggressive chordoma phenotype and poor patient survival mainly via regulating SOCS1 and TP53INP1 expression." (PMID 33194623, 2020).
coagulopathy (1 paper, 2023). "Firstly, we did not analyze the intrahepatic SOCS1 methylation status of the studied patients because it was virtually impossible to carry liver biopsy in patients with ACHBLF who had coagulopathy and high bleeding risk." (PMID 37149648, 2023).
colon adenocarcinoma (1 paper, 2015). "Besides, when compared to normal tissues, SOCS1 expression was found up-regulated in stage I and II colon adenocarcinomas (P = 0.0081 and P = 0.002, respectively, Mann Whitney test), and to a lesser extent in stage III (P = 0.0398), but not in stage IV tumours." (PMID 26391193, 2015).
colorectal adenoma (1 paper, 2024). An adenoma that arises from the colon or rectum. "Among the down-regulated genes, the researchers identified IGF2, SOCS1, MLH1, and CACNA1G as being significantly decreased in colorectal adenoma tissue samples." (PMID 38874740, 2024).
cystoid macular edema (1 paper, 2016). An autosomal dominantly inherited cystoid macular edema manifesting with macular atrophy, strabismus and, sometimes, pericentral retinitis pigmentosa. "It is, therefore, of interest to determine whether the observed efficacy of a single eye-drop of SOCS1-KIR per day pertains to other inflammatory conditions of the eye, particularly in suppressing postoperative inflammation or cystoid macular edema." (PMID 27703302, 2016).
diabetic cardiomyopathy (1 paper, 2021). Diabetic cardiomyopathy is a disorder of the heart muscle in people with diabetes. "Lastly, we studied whether the SAMe-DNMTs-SOCS1/3-IGF-1 cascade stimulated by B12 indeed mediates protection against diabetic cardiomyopathy in Elmo1H/HIns2Akita/+ mice." (PMID 34163008, 2021).
diabetic macular edema (1 paper, 2019). "The inhibition of vascular leakage was clearly demonstrated by the SOCS1 peptidomimetic because the disruption of the BRB, which is an essential step in the development of diabetic macular edema, was prevented." (PMID 31344857, 2019).
E. coli infection (1 paper, 2017). "Such factors having exclusively been induced by the E. coli infection included several TNFα induced proteins (TNFAIP230; TNFAIP331, also known as ubiquitin-editing enzyme A20; TNFAIP632) the suppressors of cytokine signaling SOCS1, SOCS333 and the NF-κB inhibitors NFKBIA, NFKBID, NFKBIE34." (PMID 28684793, 2017).
encephalitis (1 paper, 2022). An acute inflammatory process affecting the brain parenchyma. "Pathways associated with SOCS1, SHIP1, C/EBP-β, and IL13Rα1 signaling cascades might regulate the development CASPR2 encephalitis but not LGI1 encephalitis." (PMID 35083659, 2022).
endometriosis (1 paper, 2022). The growth of functional endometrial tissue in anatomic sites outside the uterine body. "SOCS1 dysregulation may exacerbate the IL-4 and IL-13 properties associated with endometriosis." (PMID 36120440, 2022).
endothelial dysfunction (1 paper, 2025). In vascular diseases, endothelial dysfunction is a systemic pathological state of the endothelium (the inner lining of blood vessels) and can be broadly defined as an imbalance between vasodilating and vasoconstricting substances produced by (or acting on) the endothelium. "Similarly, miR-155, which modulates SOCS1 and endothelial nitric oxide synthase (eNOS) and is associated with endothelial dysfunction and elevated inflammation, is found at higher levels in preeclamptic placentas." (PMID 40142811, 2025). "Additionally, miR-155 contributes to inflammation and endothelial dysfunction by downregulating the suppressor of cytokine signaling 1 (SOCS1), a negative regulator of pro-inflammatory signaling." (PMID 40142811, 2025).
eosinophilic esophagitis (1 paper, 2020). Eosinophilic esophagitis (EoE) is a chronic, allergic disease of the esophagus characterized clinically by symptoms of esophageal dysfunction (including vomiting, dysphagia, feeding disorders, food impaction and abdominal pain) which persist after treatment with proton pump inhibitors (PPIs). "In their studies, SOCS1 and SOCS3 mRNA levels were significantly increased in esophageal biopsies collected from eosinophilic esophagitis patients." (PMID 32408627, 2020).
Epileptic encephalopathy (1 paper, 2021). A condition in which epileptiform abnormalities are believed to contribute to the progressive disturbance in cerebral function. "A recent study showed a lack of TRIM8 protein expression, with suppressor of cytokine signaling 1 (SOCS1) overexpression, in podocytes and tubules from a patient with a TRIM8 variant, who presented with epileptic encephalopathy and focal segmental glomerulosclerosis (FSGS)." (PMID 34930159, 2021).
equine diseases (1 paper, 2024). "However, despite limitations, it is likely that SOCS1-KIR regulation of IFNγ, IP-10, and RANTES induced by LPS may have relevance in equine diseases." (PMID 39867889, 2024).
erythrocytosis (1 paper, 2013). "JAK2 V617F mutation and methylation analysis of SOCS1/SOCS3 CpG islands were performed in 45 cases of MPNs, 42 cases of secondary erythrocytosis/thrombocythemia, and for 29 control individuals." (PMID 24385747, 2013).
fungal keratitis (1 paper, 2025). "The exosome/let-7b-5p/SOCS-1 axis is vital for innate immunity against fungal keratitis and provides insights into the molecular mechanisms involved in this condition." (PMID 40534860, 2025). "This pathway highlights the exosome/let-7b-5p/SOCS-1 axis as a key modulator of macrophage polarization in fungal keratitis." (PMID 40534860, 2025). "This aligns with our findings that exosomal let-7b-5p suppresses SOCS1 to promote M1 polarization in fungal keratitis, suggesting that SOCS1 modulation via exosomal miRNAs is a conserved mechanism across multiple inflammatory conditions." (PMID 40534860, 2025).
gastric adenocarcinoma (1 paper, 2024). "Suppressor of cytokine signaling 1 (SOCS1), which is known to be a driver of ferroptosis, showed significant upregulation in both H. pylori-infected individuals and patients with gastric adenocarcinoma (STAD)." (PMID 39145306, 2024).
graft versus host disease (1 paper, 2025). An immune system disorder that occurs after allogeneic hematopoietic stem cell transplant and is a reaction of donor immune cells against host tissues. "For instance, in graft-versus-host disease, SOCS1 regulates the inflammatory response by suppressing T-cell activation via inhibition of the CSF3R/JAK2/STAT3 signaling pathway." (PMID 40918404, 2025).
gram-negative bacterial infections (1 paper, 2024). Infections caused by bacteria that show up as pink (negative) when treated by the gram-staining method. "Gram-negative bacterial infection activated VEGF-C/VEGFR-3 signaling in macrophages and enhanced SOCS1 (suppressor of cytokine signaling 1) expression to inhibit the TLR-4/NF-κB pathway." (PMID 38464522, 2024).
head and neck cancer (1 paper, 2021). A primary or metastatic malignant neoplasm affecting the head and neck. "SOCS1, a negative regulator of cytokine signaling pathways, was reported to regulate epigenetic modification in head and neck cancer." (PMID 34504787, 2021).
hemophagocytic lymphohistiocytosis (1 paper, 2023). "In that regard, mutations in a number of immune-regulatory genes have been described in MIS-C, including SOCS1, XIAP, and CYBB as well as HLA class I alleles and rare heterozygous mutations in genes associated with hemophagocytic lymphohistiocytosis." (PMID 36282598, 2023).
herpesvirus infection (1 paper, 2019). "The virologic, immunologic, and pathologic effects of SOCS1 or SOCS3 stimulation during herpesvirus infection frequently depend on cell type, virus strain, and host or host organ system." (PMID 31031749, 2019). "In addition to these findings with SOCS1 and SOCS3, a few studies also explore the effects of SOCS2 during α-herpesvirus infection." (PMID 31031749, 2019).
Hypertension (1 paper, 2020). The presence of chronic increased pressure in the systemic arterial system. "SOCS1 is expressed by immune cells, SOCS1 protein modulated inflammatory signaling, and it has been shown to be associated with hypertension via the JAK-STAT pathway." (PMID 32671063, 2020).
hypopharyngeal carcinoma (1 paper, 2018). Carcinoma, predominantly squamous cell, arising from the epithelial cells of the hypopharynx. "The mRNA and protein expression levels of SOCS-1, SOCS-3 and NF-κB p65 in hypopharyngeal carcinoma tissues, para-cancerous tissues and control tissues were detected by RT-PCR and Western blot analysis, respectively." (PMID 30788302, 2018). "SOCS-1 and SOCS-3 mRNA levels and protein levels were lower in hypopharyngeal carcinoma tissues than in pericarcinoma tissues, and the advanced stage patients had significantly lower level mRNA expression of SOCS-1 and SOCS-3 than those at early stages." (PMID 30788302, 2018). "The results of SOCS-1, SOCS-3, and NF-κB are available on the analysis of the pathogenesis of hypopharyngeal carcinoma." (PMID 30788302, 2018). "SOCS-1, SOCS-3 may be protective factors while NF-κB p65 could be a harmful factor in hypopharyngeal carcinoma." (PMID 30788302, 2018). "SOCS-1 and SOCS-3 may function as a tumor suppressor in hypopharyngeal carcinoma." (PMID 30788302, 2018).